HMGB1 (high mobility group box 1)
Diseases named in the same sentence as HMGB1 in open-access papers (continued):
Sharing a sentence is not in itself a finding about the gene and the disease.
Thrombocytopenia (5 papers, 2019 to 2025). A reduction in the number of circulating thrombocytes. "Synchronous changes were also observed in HMGB1-induced upregulated expression of IL-1β, and thrombocytopenia at 9 h after HS." (PMID 35945940, 2022). "HS activated the NLRP3 inflammasome, which was induced by elevated levels of ROS, while the upregulated CD62P and thrombocytopenia triggered by NLRP3 inflammasome were attributed to the high mobility group box protein 1 (HMGB1) inplasma." (PMID 35945940, 2022). "Notably, levels of secreted IL-1β, expression of CD62P, and thrombocytopenia at 9 h after HS onset were significantly alleviated after pretreatment with EP and anti-HMGB1 antibody." (PMID 35945940, 2022). "DAMPS and other mediators released from activated and injured cells such as histones and high mobility group protein B1 (HMGB1) can activate platelets and enhance agonist-induced platelet activation and granule secretion, potentiating thrombocytopenia and delaying its resolution." (PMID 31379873, 2019). "We also unraveled the role of HMGB1 in inducing NLRP3 inflammasome activation, platelet activation, and thrombocytopenia in HS." (PMID 35945940, 2022). "In conclusion, this study preliminarily demonstrates that elevated extracelluar HMGB1 induced high levels of ROS via both TLR4 and RAGE receptors of platelets, which in turn participates NLRP3 inflammasome activation leading to thrombocytopenia in HS rats." (PMID 35945940, 2022). "In this experiment, we also found that inhibiting HMGB1 by EP and anti-HMGB1 neutralizing antibody down-regulated the activation of the NLRP3 inflammasome, platelet activation, and thrombocytopenia." (PMID 35945940, 2022). "Unfortunately, whether HMGB1-induced activation of NLRP3 inflammasome is involved in platelet activation and thrombocytopenia in HS is to be elucidated." (PMID 35945940, 2022).
thymoma (5 papers, 2014 to 2022). A neoplasm arising from the epithelial cells of the thymus. "Cytoplasmic coexpression of RAGE and HMGB1 in type B thymomas and TC – TETs with a worse prognosis compared to types A and AB – is not surprising when looking at what was found in malignancies of other origins." (PMID 24705787, 2014). "The moderate cytoplasmic staining intensity of HMGB1 in B2 thymomas was comparable to that of cTEC, the weak intensity of B3 thymomas to that of thymocytes." (PMID 24705787, 2014). "HMGB1 showed higher expression in type A, B1, and B2 of thymomas compared to thymic carcinomas." (PMID 36551568, 2022). "The results for HMGB1 were as follows: One-way ANOVA: p = 0.296; TC vs. thymoma: p = 0.729, thymoma vs. TH: 1.000, TC vs. TH: p = 0.385." (PMID 24705787, 2014). "Further stratification of patients with TETs into patients with TCs and thymomas compared to volunteers revealed significant differences in sRAGE and HMGB1 levels in serum but not in esRAGE levels (sRAGE [pg/ml] TC 188.6±40.5 vs. thymoma 291.8±47.1 vs. control 364.8±28.6; p = 0.008; fig." (PMID 24705787, 2014). "Conversely, there was no expression of HMGB1 in the cytoplasm of WHO type A and AB thymomas, strong cytoplasmic staining in neoplastic epithelial cells of types B1, moderate in type B2, and weak in type B3 and TC." (PMID 24705787, 2014). "Carcinogenesis could be promoted through binding of HMGB1 (elevated in TC patients), that is not scavenged by sRAGE/esRAGE, to the cell-surface bound RAGE receptor on nascent transformed cells (thymoma, TC)." (PMID 24705787, 2014).
Ureteral obstruction (5 papers, 2023 to 2025). Obstruction of the flow of urine through the ureter. "Increased expression and release of HMGB1 in kidneys subjected to unilateral ureteral obstruction (UUO) have been shown to promote interstitial fibrosis by inducing M1 macrophage polarization; conversely, blocking HMGB1 release or counteracting its function alleviates inflammation and fibrosis." (PMID 40877572, 2025). "A preclinical study also found that in the early stage after unilateral ureteral obstruction, renal tubular HMGB1 deletion had no obvious effect on renal injury, but it can significantly reduce renal interstitial fibrosis in the late/subacute stage." (PMID 38481996, 2024).
xerostomia (5 papers, 2021 to 2025). Dryness of the mouth resulting from reduced salivary secretion. "In an SS model, inhibition of HMGB1 improved xerostomia triggered by SS by suppressing the HMGB1/TLR4/NF‐κB signaling pathway and upregulating AQP5 expression." (PMID 40656544, 2025). "Inhibiting HMGB1 reduces SS-induced xerostomia by inhibiting the HMGB1/TLR4/nuclear factor-kappa B (NF-κB) signaling pathway and increasing AQP5 expression." (PMID 35628481, 2022). "As an alarmin, HMGB1 is also a potential therapy target in SS, and researchers found that suppression of HMGB1 ameliorates SS-triggered xerostomia in a mouse model." (PMID 35411013, 2022). "Xerostomia was reversed in mice treated with anti-HMGB1 due to increased saliva production and lower anti-SSB levels." (PMID 35628481, 2022).
abdominal aortic aneurysm (4 papers, 2023 to 2025). Enlargement and ballooning of the vessel that supplies arterial blood to the abdomen, pelvis and legs. "Additionally, compared to controls, patients with an abdominal aortic aneurysm (AAA) demonstrated increased aortic tissue HMGB1." (PMID 38275751, 2023). "A positive correlation between increased HMGB-1 serum levels and enhanced protein expression in endothelial and vascular smooth muscle cells, atherosclerotic plaques and inflammatory cells located in the media and adventitia has been demonstrated in patients with abdominal aortic aneurysm." (PMID 37513606, 2023).
acute leukemia (4 papers, 2017 to 2025). A clonal (malignant) hematopoietic disorder with an acute onset, affecting the bone marrow and the peripheral blood. "In acute leukemia, HMGB1/RAGE signaling increases P-gp and MRPs expression, concurrently enhancing autophagy and suppressing apoptosis to create a survival-permissive state." (PMID 41465435, 2025). "In conclusion, the present study demonstrates the role HMGB1/RAGE axis plays in promoting acute leukemia cells survival by diminishing apoptosis and increasing autophagy and the expression of multiple drug resistant protein." (PMID 34933679, 2021). "High-mobility group box 1 (HMGB1) has been proven to have a important role in drug resistance via upregulation of autophagy after chemotherapy treatment in acute leukemia." (PMID 34933679, 2021). "In an attempt to characterize the role HMGB1 plays in acute leukemia, western blotting and HMGB1 Elisa kit were employed to analyze the expression of HMGB1." (PMID 34933679, 2021). "Interfering with HMGB1/RAGE can be a potential means to cure acute leukemia." (PMID 34933679, 2021). "Furthermore, the HMGB1/RAGE axis not only activates ERK to inhibit mTOR and induce autophagy but also activates NF-κB to upregulate drug efflux pumps like P-glycoprotein (P-gp) and MRP, creating a multi-faceted defense system against chemotherapeutic agents in acute leukemia." (PMID 41465435, 2025).
acute-on-chronic liver failure (4 papers, 2014 to 2022). Acute-on-chronic liver failure (ACLF) is an extreme condition during the natural history of chronic HBV infection, with a relatively high short-term mortality. "High mobility group box chromosomal protein 1 (HMGB1) is an important proinflammatory molecule in a number of inflammatory disorders, but little is known about its role in acute-on-chronic liver failure (ACLF)." (PMID 25187820, 2014).
adenovirus infection (4 papers, 2021 to 2025). "These latter data show that all cell types used in the study were successfully infected, and confirms cell type-specific trafficking of HMGB1 upon adenovirus infection." (PMID 40367285, 2025). "To better understand the complexity of corneal epithelial cell responses to adenovirus infection beyond HMGB1 secretion, and the potential for additional cross-talk with the underlying keratocytes, we also infected or mock-infected PCEC and THE cells for proteome analysis." (PMID 40367285, 2025). "To discern whether HMGB1 secretion following adenovirus infection of corneal epithelial cells might occur through a pyroptotic pathway, we tested for byproducts of pyroptosis up to 48 hpi." (PMID 40367285, 2025). "Therefore, the impact of HMGB1 on HCF in adenovirus infection is likely additive." (PMID 40367285, 2025). "We applied HCM using CRM1 knockdown (siCRM1) and negative control (NC-siRNA) treated cells followed by adenovirus infection for 12 h, a time when HMGB1 nuclear to cytoplasmic translocation was clearly evident in prior experiments." (PMID 40367285, 2025). "Exogenous HMGB1 also induces a robust expression of proinflammatory mediators by corneal stromal cells, consistent with both cell types contributing to SEI formation upon adenovirus infection of the human cornea." (PMID 40367285, 2025). "Additionally, the mcherry-EGFP-LC3 adenovirus infection and Western blotting results showed that the number of autophagosomes, Beclin 1 protein abundance, and LC3-II/LC3-I ratio decreased after HMGB1 knockdown." (PMID 38468340, 2024). "Additionally, since adenovirus infection did not alter levels of total HMGB1 mRNA or protein in corneal epithelial cells, it appears to be specifically the post-translational acetylation of HMGB1 that mediates its secretion." (PMID 40367285, 2025). "To test our hypothesis, we generated cell lines expressing different constructs of HMGB1 with a GFP tag and visualized localization in the presence or absence of adenovirus infection." (PMID 37703278, 2023).
age-related macular degeneration (4 papers, 2019 to 2025). Age-related loss of vision in the central portion of the retina (macula), secondary to retinal degeneration. "In age-related macular degeneration, the upregulation of both HMGB1 and CAV1 has been implicated in retinal pigment epithelium cell senescence." (PMID 40362460, 2025). "This study aims to compare serum HMGB-1, 3-nitrotyrosine (3-NT), TAS, TOS, and OSI levels in Wettype Age-Related Macular Degeneration (wAMD) patients and healthy controls to determine the correlation of these parameters with each other." (PMID 36042902, 2022).
Atrophy (4 papers, 2020 to 2025). Any weakening or degeneration, especially through lack of use. "Fr‐HMGB1 can recruit stem cells and macrophages strongly associated with muscle atrophy." (PMID 39963819, 2025). "In CKD samples with multifocal tubular atrophy and interstitial fibrosis, there was a significant increase in HMGB1 expression in tubular cells and an increased rate of nuclear p65." (PMID 37284446, 2023).
autism spectrum disorder (4 papers, 2017 to 2025). A spectrum of developmental disorders that includes autism, and Asperger syndrome. "Alterations in HMGB1 serum concentrations have been observed in childrenwith autism spectrum disorder, with elevated levels reported." (PMID 41209506, 2025). "High mobility group box 1 protein (HMGB1) has been suggested to be involved in the immune dysfunction and inflammation reported in autism spectrum disorder (ASD)." (PMID 34198762, 2021). "Overview of the original research studies investigating the role of HMGB1 in autism spectrum disorder." (PMID 29682486, 2017). "More larger-scale studies are needed to be performed to clarify the role of HMGB1 in the pathogenesis of autism spectrum disorder, potentially leading to novel disease markers and targeted therapeutics." (PMID 29682486, 2017). "In summary, increased HMGB1 levels have been found in the blood of young and adult patients with autism spectrum disorder." (PMID 29682486, 2017).
autoimmune hepatitis (4 papers, 2014 to 2024). Hepatitis caused by autoantibodies. "Glycyrrhizin, which directly binds to HMGB1, rendering it unavailable for interaction with its receptors, has already been investigated in clinical trials including in autoimmune liver diseases." (PMID 39000266, 2024). "Collectively, these data imply that there are other mechanisms involved in mediating the effects of ethyl pyruvate on HMGB1 in Con A-induced autoimmune hepatitis." (PMID 24498418, 2014). "The elevation of ANA against histone H1 or HMGB1 in PBC patients and the elevation of biliary HMGB1 in PSC patients also suggest that histone H1 and HMGB1 may act as a potential therapeutic target in autoimmune liver diseases." (PMID 39273280, 2024). "Here, we explored whether ethyl pyruvate ameliorated inflammation by decreasing the expression of HMGB1 in Con A-induced autoimmune hepatitis in mice." (PMID 24498418, 2014). "The purpose of our study was to determine whether ethyl pyruvate could inhibit the expression and release of both early (TNF-α, IL-2, IL-6, IL-1β) and late (HMGB1 ) cytokines in Con A-induced autoimmune hepatitis." (PMID 24498418, 2014). "Taken together, these results indicated that ethyl pyruvate protected against Con A-induced autoimmune hepatitis by decreasing both early (TNF-α, IL-2, IL-1β and IL-6) and late (HMGB1) cytokine expression in mice." (PMID 24498418, 2014). "Pretreatment with ethyl pyruvate ameliorated the pathological effects of Con A-induced autoimmune hepatitis and significantly decreased the levels of TNF-α, IL-2, IL-6 and IL-1β at 3h and 6h and the level of HMGB1 at 6h and 24h post injection." (PMID 24498418, 2014).
bladder urothelial carcinoma (4 papers, 2015 to 2025). "Furthermore, the HMGB1 role was described in the bladder urothelial carcinoma as it is involved in fostering malignancy and pathogenesis." (PMID 35829833, 2022). "However, there have been few studies of the function of HMGB1 in the malignant biological behaviour of bladder urothelial carcinoma (BUC), and the potential mechanism of HMGB1 in the pathogenesis of BUC remains unclear." (PMID 26239046, 2015).
brain glioma (4 papers, 2018 to 2022). A malignant glioma that involves the brain. "MiR-339-5p is a tumor suppressor, inhibiting PTP4A1/HMGB1 signal pathway it suppresses vasculogenic mimicry, migration, and invasion of brain glioma U251 cells." (PMID 36354672, 2022). "MiR-339-5P inhibits angiogenic mimicry, migration, and invasion of brain glioma U251 cells by inhibiting the PTP4A1/HMGB1 signal pathway." (PMID 35872698, 2022). "TP73-AS1 promotes brain glioma growth and invasion by sponging miR-142 to promote HMGB1 expression." (PMID 29552296, 2018). "On the contrary, TP73-AS1 could promote tumor progression through regulating HMGB1/RAGE pathway in GC, brain glioma and HCC." (PMID 32493915, 2020).
carotid atherosclerosis (4 papers, 2014 to 2022). A thickening and loss of elasticity of the walls of carotid arteries that occur with formation of atherosclerotic plaques. "However, further studies are needed to confirm the role of HMGB1 in carotid atherosclerosis and to clarify the pathophysiological mechanisms underlying plaque instability." (PMID 34044825, 2021). "Surprisingly, the carotid artery specimen revealed a decreased expression of HMGB1 and S100B with a concomitant increase in the pro-inflammatory cytokines IL-17, IL-18 and IL-1β suggesting the priming role of DAMPs in initiating carotid atherosclerosis." (PMID 35531433, 2022). "Twenty-three GPA patients and 20 controls were evaluated for HMGB1- and sRAGE levels and for carotid atherosclerosis using ultrasound to determine intima-media thickness (IMT)." (PMID 24776932, 2014). "sRAGE was associated with subclinical carotid atherosclerosis whereas HMGB1 was not." (PMID 24776932, 2014).
cerebrovascular disease (4 papers, 2020 to 2024). "In this context, high motility group box 1 (HMGB1), a DNA-binding protein known to be associated with cerebrovascular disease, was suggested to play a critical role in inducing NETosis." (PMID 35682594, 2022). "We revealed that Tim-3 aggravates neuroinflammation and deteriorates neurocyte apoptosis through the Nrf2/HMGB1 signaling pathway after acute SAH in rats, which may expand application in the future development of effective therapeutic approaches against cerebrovascular diseases." (PMID 33168786, 2020).
cholestasis (4 papers, 2020 to 2024). Impairment of the bile flow caused by obstruction within the liver, or outside the liver in the bile duct system. "In instances of liver tissue injury, such as in cholestasis, HMGB1 is released resulting in inflammation and progression of the disease." (PMID 39349582, 2024). "Our results indicate that bicyclol is a promising therapeutic strategy for cholestasis by regulating the bile acids and autophagy-mediated HMGB1/p62/Nrf2 pathway." (PMID 34366845, 2021).
chronic myeloid leukemia (4 papers, 2020 to 2022). "High expression of HMGB1 is associated with the progression of lymphocytic leukemia and chronic myeloid leukemia." (PMID 33128580, 2021). "It inhibits the interactions between RAGE and its ligands, including Aβ1-42, HMGB1 (high mobility group box 1), S100B, and CML (chronic myeloid leukemia)." (PMID 36389082, 2022). "In chronic myeloid leukemia (CML), HMGB1 knockdown can arrest the cell cycle at the G1 phase and inhibit cell proliferation by downregulating the expression of cyclooxygenase-2 (COX-2)." (PMID 32660524, 2020).
co-infection (4 papers, 2011 to 2024). "It was found that co-infection (virus and bacteria) can be concluded when HMGB1 expression is greater than 1.0256." (PMID 31918745, 2020). "Elevated circulating HMGB1 in PWH with HBV co-infection who are progressors could be related to higher levels of hepatocyte death, however, we are unable to confirm this in an observational study." (PMID 38518655, 2024). "Reversely, the alarmin activity of HMGB1 may be detrimental, notably in HSV-2/HIV co-infection." (PMID 21283827, 2011).
cutaneous squamous cell carcinoma (4 papers, 2017 to 2021). "Intracellular HMGB1 induces cell proliferation, migration, and invasion via the MAPK and/or PI3K/Akt signalling pathways in malignancies, including myofibroblasts and human cutaneous squamous cell carcinoma." (PMID 29246127, 2017).
E. coli infection (4 papers, 2011 to 2025). "To determine the effect of PGD2 on the damage caused by E. coli infection in BMDMs and bovine endometrial tissues, we measured the expression of DAMPs (HMGB-1, HABP-2) using qPCR and immunofluorescence." (PMID 40874199, 2025). "To investigate the effect of inhibiting the mPGES-1–PGE2 axis on the expression of DAMPs during E. coli infection, we measured the mRNA levels of key DAMPs, such as HMGB-1 and HABP-2, in BMDM following treatment with mPGES-1 inhibitors (MF63 and MK886)." (PMID 40666730, 2025). "To examine the impact of inhibiting the PGE2-EP4 axis on DAMPs expression during E. coli infection, we assessed the mRNA expression of HMGB-1 and HABP-2 in BMDM." (PMID 40666730, 2025). "The results showed that E. coli infection significantly upregulated the expression of both HMGB-1 and HABP-2 compared to the control group." (PMID 40666730, 2025). "By western blot analysis there is a significant increase in the level of HMGB1 after E. coli infection in both wild type and RAGE KO mice." (PMID 21629785, 2011). "We also measured lactate dehydrogenase (LDH) and high mobility group protein 1 (HMGB-1) levels in the BALF, both of which are released during lytic cell death, and observed significantly higher levels of LDH and HMGB-1 in the BALF of the Casp1+/+ mice after E. coli infection." (PMID 40359428, 2025). "E. coli infection significantly increased the expression of both HMGB-1 and HABP-2 in BMDM." (PMID 40666730, 2025). "Compared to the E. coli infection group, PGD2 significantly increased HMGB-1 and HABP-2 mRNA expression levels in BMDMs (P < 0.05)." (PMID 40874199, 2025).